GPX1 (glutathione peroxidase 1)
Diseases named in the same sentence as GPX1 in open-access papers (continued):
Sharing a sentence is not in itself a finding about the gene and the disease.
cancer (146 papers, 2004 to 2025). A tumor composed of atypical neoplastic, often pleomorphic cells that invade other tissues. "The GPx1 gene, for example, acts as an anti-oncogene, and mutations in this gene are positively associated with increased cancer risk." (PMID 39942544, 2025). "In recent years, GPX1 has been well identified as closely linked to the pathogenicity of various cancer types." (PMID 40346054, 2025). "In animal models, the loss of both GPx1 and GPx2 results in ileocolitis and spontaneous cancer, underscoring the importance of these enzymes in cancer prevention." (PMID 39942544, 2025). "A GPx1 deficiency can worsen cardiac dysfunction, while its overexpression or increased activity has been linked to poor prognosis in various cancers." (PMID 39594513, 2024). "Several studies have shown that GPx1 is associated with cancer when its expression is inhibited or reduced in particular." (PMID 39839762, 2024). "GPx1 has been implicated in the development and prevention of numerous cardiovascular diseases and cancer." (PMID 38891864, 2024). "What’s more, GPX1, ubiquitously expressing in many tissues, has been reported to have an aberrant expression in multiple cancers and be closely associated with oncogenesis and cancer progression." (PMID 38659038, 2024). "The relationship between the genetic polymorphism of GPx1 and cancer development has also been explored in various types of cancers." (PMID 38398797, 2024). "Several studies revealed that high or low levels of Gpx-1 expression can be associated with cancer development, mainly through its role in hydroperoxide scavenging by regulating intracellular ROS." (PMID 37242524, 2023). "The GPX1 Pro198Leu polymorphism is being intensively studied in various types of cancer, urinary bladder, breast cancer, lung, prostate, colon and leukaemia." (PMID 37446063, 2023). "Gpx-1 is closely associated with the development of tumours and with the survival and prognosis of patients in a wide range of human malignant tumours." (PMID 37242524, 2023). "Pro198Leu GPx1 polymorphism is associated with various types of cancer, mainly breast, prostate, lung, bladder, leukemia, and colon cancers." (PMID 38202704, 2023). "They reported that variant GPX1-Leu allele carriers (Pro/Leu and Leu/Leu) have increased cancer risk, especially in Asian subgroups in a dominant genetic model." (PMID 36676755, 2023). "Several studies revealed that expression levels of glutathione peroxidase 1 (Gpx-1) can be associated with cancer development, mainly through its role in hydroperoxide scavenging by regulating intracellular reactive oxygen species (ROS) levels." (PMID 37242524, 2023). "In this review, we comprehensively summarize the controversial associations between GPX1 polymorphism and cancer risks and further discuss the relationships between the aberrant expressions of GPX1 and tumorigenesis." (PMID 35626163, 2022). "In some malignant tumors, the increased expression of GPX1 is associated with carcinogenic outcomes." (PMID 36432484, 2022). "GPX1 polymorphism has type-specific effects as a candidate marker for cancer risk, but the association between GPX1 variants and cancer susceptibility remains controversial in different studies." (PMID 35626163, 2022). "Some selenoproteins have been reported to paradoxically exert adverse consequences in certain contexts, including increased insulin sensitivity in GPx1 KO mice and increased cancer resistance in TrxR1-deficienct hepatocarcinoma and lung carcinoma cells." (PMID 35204134, 2022). "Particularly, the interaction between genetic factors and the dietary selenium intake seems to be effective in determining cancer risk and outcome via the metabolism of pivotal selenoproteins such as SelP, SelF (Selenoprotein F), GPx4, and GPx1." (PMID 35204134, 2022).
cancer (continued). "Numerous case-control studies and meta-analyses have assessed the association between a functional genetic polymorphism of the GPX1 gene, named Pro198Leu (rs1050450 C>T), and cancer susceptibility in different populations." (PMID 35626163, 2022). "Many studies have already reported that GPX1 gene polymorphisms have complex associations with cancer risks and patient survival." (PMID 35626163, 2022). "Pentathiepins can effectively inhibit GPX1 enzymatic activity and induce a loss of mitochondrial membrane potential and oxidative stress in cancer cells, resulting in DNA strand breaks and apoptosis." (PMID 35626163, 2022). "The GPX1 (rs1050450) polymorphism has been studied for the following cancers so far: breast, prostate, bladder, lung, head, neck and brain." (PMID 35205233, 2022). "It is now well recognized that GPX1 is closely linked to the pathogenicity of various types of cancer." (PMID 35626163, 2022). "Although great efforts have been made to explore the association between GPX1 Pro198Leu gene polymorphism and cancer risks, the role of GPX1 polymorphism is yet to be further elucidated." (PMID 35626163, 2022). "Many authors advocate SNP rs1050450 in the GPX1 gene to contribute to susceptibility to various cancers." (PMID 33953831, 2021). "Mutations in the Gpx1 gene increased the risk of developing cancer, whereas overexpression of normal selenoprotein showed a protective role." (PMID 34068374, 2021). "Pentathiepins inhibit glutathione peroxidase 1 (GPx1), cause a loss of mitochondrial membrane potential as well as oxidative stress in cancer cells, resulting in DNA strand breaks and inducing apoptosis." (PMID 32311219, 2020). "GPx1 loss is associated with the development of various types of cancer, including breast, lung, prostate, and bladder cancers." (PMID 32380763, 2020). "Several studies have demonstrated an association between GPx1 and cancer when expression is repressed or reduced." (PMID 32414091, 2020). "For PC2, top positively correlated genes included IFITM1 and GPX1, both have been reported to be associated with risk of numerous cancers, while most negatively PC2 correlated genes included common-known tumor over-expressed genes such as EFNA1." (PMID 32231683, 2020). "This is partly supported by the strongest association (by PIGE) in pathway 1 for gene variance in GPX1, which has been previously implicated in risk of various cancers." (PMID 31027226, 2019). "Many studies have linked GPx1 to cancer initiation and progression in various stages of carcinogenesis." (PMID 30538220, 2018). "Among the 25 human selenocysteine-containing proteins, there is considerable evidence that the cytosolic form of GPX1 is associated with cancer risk." (PMID 29535818, 2018). "Only an overall association of GPX1 Pro198Leu with grade of cancer (Pro/Leu vs. Pro/Pro: p = .0200) was detected." (PMID 29411539, 2018). "Accordingly, the identification of a well‐characterized functional polymorphism named p.Pro198Leu (rs1050450 C>T) in GPX1 gene, a lot of studies have been conducted to evaluate the association between p.Pro198Leu polymorphism and risk of cancer development." (PMID 29411539, 2018). "The SNP rs1050450 (or GPX1 Pro198Leu) has been studied extensively in human disease and has already been linked to cancer risk, and oxidative stress related diseases." (PMID 28052094, 2017). "It has been reported that GPX1 gene polymorphism (GPX1 Pro198Leu) is associated with decreased enzyme activity, thereby conferring an increased risk of developing cancer in Caucasians." (PMID 26823947, 2016). "ROS is a primary inducer of many ageing‐related human diseases such as neurodegeneration and cancer, which are also associated with the loss of GPX1 activity." (PMID 27286733, 2016).
cancer (continued). "Our results showed linear, up-regulation of Prdx3 and Gpx1 in the middle section of small intestine; this can activate antioxidant processes that are relevant for bacteria-associated inflammation, cancer-promoting conditions and tumor progression." (PMID 26861690, 2016). "In vitro, animal studies, and human genetics all suggests that decreased levels of GPx-1 is correlated with increased risk of cancer." (PMID 27023612, 2016). "In particular, rs1050450 (GPX1) has been linked to other cancers such as lung, bladder and laryngeal cancers." (PMID 25988760, 2015). "The impact of cys57 on the interaction between SBP1 and GPx1 was investigated in MCF7 cells that were either null for GPx1 or expressed different GPx1 alleles previously shown to differ in cancer risk and cellular location." (PMID 26593911, 2015). "Among those features impacted was its interaction with GPx1, a protein implicated in the risk of cancer and other diseases by human genetics as well as the propagation of signal pathways relevant to cancer and other pathologies." (PMID 26593911, 2015). "It has been reported that the GPX1 Pro198Leu polymorphism is associated with an increased risk of developing bladder, breast, and lung cancer, due to a reduction in enzymatic production and activity." (PMID 25436036, 2014). "Polymorphisms in the GPx-1 gene (locus 3p21.3, OMIM, +138320) have been related to enhanced risk of cancer and some studies have indicated that the Leu variant of GPx-1 gene affects the activity of enzyme GPx-1, which becomes less responsive to stimulation." (PMID 20444272, 2010). "In the case of cancer, it is known that in cell culture both GPx1 and GPx2 can prevent oxidative DNA mutations and counteract the production of proinflammatory mediators derived from cyclooxygenase (COX)/lipoxygenase (LOX), such as prostaglandins and leukotrienes." (PMID 38891864, 2024). "Decreased levels of GPx-1 may result in the initiation of carcinogenesis, and in later stages of cancer, GSH-Px deficiency may even cause proliferative effects." (PMID 38540964, 2024). "However, the association between GPX1 genetic variants and cancer susceptibility is still controversial and inconclusive probably due to the differences in study cohorts and statistical methods." (PMID 36676755, 2023). "However, the connection between GPx1 polymorphism and cancer vulnerability is controversial and inconclusive." (PMID 38202704, 2023). "The associations between GPX1 polymorphisms and cancer risks." (PMID 35626163, 2022). "In this review, we summarize and discuss the relationship between GPX1 genetic polymorphisms and cancer susceptibility, as well as the dichotomous roles of GPX1 aberrant expressions in the occurrence and development of human malignancies via various biological mechanisms." (PMID 35626163, 2022). "Artificially altering the expression and distribution of GPX1 in the cellular cytoplasm and mitochondria leads to changes in oxidative stress, energy metabolism, and cancer signaling pathways, suggesting that genetic polymorphism and cellular location of GPX1 can affect cell biology." (PMID 35626163, 2022). "GPX1 has been associated with carcinogenesis and the progression of cancer." (PMID 36432484, 2022). "A comprehensive meta-analysis including 31 published articles found that GPX1 Pro198Leo polymorphism may promote cancer susceptibility by disturbing the antioxidant balance." (PMID 35626163, 2022). "However, the associations between GPX1 genetic variants and cancer susceptibility are still controversial and inconclusive due to the differences in study cohorts and statistical methods." (PMID 35626163, 2022). "When these cancer cells were transfected with a siRNA specific to GPx1, the resulting depletion of GPx1 caused markedly augmented TNF-α-induced apoptosis of all the cancer cells selected, which were then completely blocked by treatment with a pan-caspase inhibitor (zVAD-fmk)." (PMID 34158609, 2021).
cancer (continued). "In addition, the GPX1 rs1050450 mutant variant has been related to decreased GPX1 activity in cancer patients." (PMID 33672092, 2021). "Studies have implicated the role of Gpx1 in some cancers and cardiovascular diseases in humans." (PMID 34679770, 2021). "In addition to GPX1 polymorphisms, polymorphisms in other selenoprotein genes have been linked to cancer risk when assessed in conjunction with selenium status." (PMID 32806741, 2020). "GPX1 variations also affect the distribution of the protein between the mitochondria and the cytoplasm, which impacts cellular energy metabolism, mitochondrial function, and expression of proteins associated with cancer progression." (PMID 32806741, 2020). "During the last decades, a great interest was given to GPX1 as a determinant of cancer risk." (PMID 29411539, 2018). "Although the GPX-1 Pro198Leu polymorphism has been exhaustively studied in relation to cancer, the study in Ecuador identified the prevalence of the Leu allele of the GPX-1 gene in glyphosate-exposed individuals that suggests a higher risk of DNA damage and increased sensitivity to herbicides." (PMID 22496977, 2012). "This review aims to summarize the molecular structure, function of GPX1, and its roles in redox regulation and further highlight the studies focused on its roles and underlying mechanisms in multiple human cancers to evaluate its therapeutic and prognostic values for cancers." (PMID 35626163, 2022). "Some insights into a possible beneficial effect of Se supplementation specifically in GPX1 LeuLeu individuals may be obtained by the analysis of the relationship between GPX1 rs1050450 polymorphism and cancer risk-related biomarkers, such as DNA damage, in the Se supplemented individuals." (PMID 26658762, 2016). "Two genetic variations in the human GPx-1 gene, a variable number of alanine-encoding triplets in the 5′- end of the gene and either a codon for alanine or proline at position 198 have been described and these have been shown to associated with several diseases including cancer." (PMID 26007340, 2015). "Reduced levels of GPX-1 may increase the risk or promote the development of cancer." (PMID 24228025, 2013). "Thus, study of the joint effect of the MnSOD, nitric oxide synthase, and GPX1 gene polymorphisms might provide further information on the role played by oxidative stress in cancer risk." (PMID 15535847, 2004). "Aberrant expression of GPX1 in various cancer types is closely related to oncogenesis or cancer progression." (PMID 40346054, 2025). "GPx1 is an essential antioxidant enzyme that is crucial for maintaining cellular redox balance by controlling ROS levels and has a multifaceted role in cancer." (PMID 40179084, 2025). "In multiple cancer types, such as bladder and throat cancers, studies have shown that Gpx1 expression levels are strongly correlated with prognosis." (PMID 39857814, 2025). "The GLS1 inhibitor synergizes with the GPX4 inhibitor to inhibit tumour growth, and dual suppression of GPX4 and GPX1 offers a potent anti‐cancer strategy." (PMID 40259435, 2025). "The role of GPx1 in various cancers is complex, however, its overexpression significantly impacts tumor behavior, influencing processes like cell proliferation and apoptosis." (PMID 40179084, 2025). "We also show that dual inhibition of GPX4 and GPX1 synergistically inhibits cancer cell growth, validating the effectiveness of targeting this compensatory metabolic mechanism." (PMID 40259435, 2025). "GPX1 is overexpressed in various tumors to induce drug resistance, and many studies have been exploring inhibitors for cancer therapy." (PMID 40346054, 2025). "Selenoproteins, particularly GPx1, GPx3, TrxR, SELENOP, SELENOM, SELENOS, SPS1, and SPS2, are essential in regulating oxidative stress and cancer risk." (PMID 39942544, 2025).
cancer (continued). "Inhibiting GLS1 enhances the efficacy of ferroptosis inhibitors in suppressing tumour growth, and simultaneously targeting GPX4 and GPX1 offers a powerful anti‐cancer approach." (PMID 40259435, 2025). "The studies of the functions of GPx5, GPx6, GPx7, and GPx8 in cancer development are limited in comparison with those of Gpx1–Gpx4." (PMID 39125992, 2024). "In most types of cancer, GPx1 acts as a tumor promoter by regulating the proliferation, invasion, migration, apoptosis, immune response, and drug sensitivity of tumor cells." (PMID 39125992, 2024). "It has been reported that the ferroptosis regulatory system (GPX4) and anti-oxidative enzymes (GPX1) contribute to anti-cancer drug resistance." (PMID 38182643, 2024). "Experimental mouse models revealed that selenium via GPx1 provides a partial protective effect against some types of cancer." (PMID 38483584, 2024). "Specifically, it has been shown that the increased activity of GPX1 in cancer cells leads to a decrease of the intracellular level of hydrogen peroxide." (PMID 36676755, 2023). "There is accumulating evidence connecting the GPX1 and SOD2 genetic variants with cancer development, disease progression, and treatment outcomes in a different types of cancers." (PMID 36676755, 2023). "Recent studies have also found that upregulation of GPX1 expression induces drug resistance in cancer cells by reducing ROS produced by platinum-based chemotherapy drugs." (PMID 37299554, 2023). "GPX1 overexpression can eliminate reactive oxygen species, inhibit apoptosis and induce drug resistance, promoting cancer cell survival." (PMID 37446063, 2023). "Fumarate can bind to and activate the ROS-scavenging enzyme glutathione peroxidase 1 (GPx1), conferring metabolic advantages for cancer cell growth and proliferation." (PMID 36959802, 2023). "By use of the Western blot method, we assessed the expression of Gpx-1 in three distinct cancer cell lines and in a control cell line." (PMID 37242524, 2023). "Western blot analysis was used for the evaluation of Gpx-1 protein expression levels in cancer cell lines in vitro." (PMID 37242524, 2023). "Regarding cancer, it has been extensively described that GPx-1 protein levels and gpx1 mRNA expressions are upregulated in tumor (carcinoma) tissues to protect against DNA damage due to their association with an increased risk of cancer." (PMID 37761814, 2023). "This modification supports the translation of reactive oxygen species (ROS)-detoxification enzymes, such as glutathione peroxidase 1 (Gpx1), enabling cancer cells to exploit oxidative stress conditions." (PMID 38201505, 2023). "Studies have shown that Gpx-1 can regulate cancer cell proliferation, invasion, migration, apoptosis, immune response, and drug sensitivity." (PMID 37242524, 2023). "The overexpression of GPX1 in various tumors can eliminate ROS, weaken apoptosis, and induce drug resistance, promoting cancer cell survival." (PMID 35626163, 2022). "Bioinformatics analysis of RNA sequencing data from 31 types of cancers in TCGA revealed that high GPX1 expression levels indicate worse OS and disease-free survival (DFS) prognosis in LGG and AML but better OS in KIRP." (PMID 35626163, 2022). "Transcriptome-sequencing data from the Cancer Genome Atlas (TCGA) public database revealed that GPX1 is highly expressed in most cancers and has higher expressions in tumor tissues than adjacent normal controls." (PMID 35626163, 2022). "GPX1 is abnormally elevated in most types of cancer but has complex dichotomous roles as tumor suppressor and promoter in different cancers." (PMID 35626163, 2022). "GPX1 silencing in RIPK3-negative cancer cells significantly increases H2O2 levels, sustains the activation of JNK and Caspase-8, and promotes TNF-α-induced apoptosis." (PMID 35626163, 2022). "For instance, GPX1, dramatically downregulated in various cancers, is a negative regulator for cancer progression." (PMID 35566360, 2022).